SHBG (sex hormone binding globulin)
Diseases named in the same sentence as SHBG in open-access papers (continued):
Sharing a sentence is not in itself a finding about the gene and the disease.
Insulin resistance (continued). "High androgen levels in women with insulin resistance can also be due to inhibition of hepatic production of sex hormone-binding globulin (SHBG)." (PMID 21849061, 2011). "Distinct features in women with PCOS, insulin resistance and compensatory hyperinsulinemia, lead to hyperandrogenemia due to increased ovarian androgen production and decreased production of sex hormone binding globulin." (PMID 21605417, 2011). "Insulin resistance leads to hyperinsulinaemia, reduces SHBG and raises free circulating testosterone and together, hyperandrogenism and hyperinsulinaemia impairs ovarian follicle development." (PMID 20591140, 2010). "Not surprisingly, following discontinuation of insulin sensitization therapy there was an initial partial convergence between the two groups in levels of insulin resistance and sex hormone binding globulin (SHBG) from 36 months to 48 months." (PMID 17608755, 2007). "It seems higher than clinical expectation because that our subjects, enrolled from infertility/endocrine/obesity clinics, have higher body weigh and lower SHBG which are correlated with incidence of insulin resistance and AGT." (PMID 16603055, 2006). "We were also interested in exploring the interaction with diabetes mellitus as insulin resistance can lead to increased levels of plasma insulin, lower levels of plasma sex hormone binding globulin and, consequently, increased levels of free estrogen." (PMID 16280037, 2005). "Studies have shown that endogenous sex hormones play a crucial role in the pathogenesis of diabetes and that elevated levels of SHBG, bioavailable testosterone, and estradiol are associated with insulin resistance and glucose levels independent of adiposity." (PMID 38912813, 2025). "A decrease in SHBG production during hepatic insult or metabolic dysfunction results in fewer hormones being bound, leading to an increase in free active androgens, promoting hyperandrogenism and insulin resistance." (PMID 40650160, 2025). "In line with this, lower SHBG levels, but not higher testosterone, have shown to be independently associated with insulin resistance in women with PCOS who are overweight." (PMID 39996383, 2025). "Insulin resistance may promote ovarian and adrenal hormone production, may augment the frequency of LH release, and may inhibit the production of SHBG, which, in turn, elevates testosterone activity." (PMID 39997347, 2025). "In addition, insulin resistance increases serum ovarian and adrenal-derived androgens and decreases sex hormone-binding globulin (SHBG) levels." (PMID 40095159, 2025). "Moreover, insulin resistance, as evaluated by IRI, was significantly associatedwith decreased serum SHBG and TT." (PMID 40857627, 2025). "The suppression of sex hormone-binding globulin (SHBG) synthesis represents a critical mechanism whereby insulin resistance amplifies estrogenic stimulation of endometrial tissue, creating a hormonal environment that synergizes with direct metabolic effects to promote carcinogenesis." (PMID 41301707, 2025). "In addition, other studies have shownthat sex hormone binding globulin (SHBG) is closely related to systemic metabolismand that SHBG can reflect a variety of circulating lipid and metabolite changesrelated to insulin resistance." (PMID 40232167, 2025). "Additionally, studies have indicated that a reduction in SHBG levels contributes to the development of NAFLD, making it a sensitive biomarker of NAFLD, and SHBG is suggested as a surrogate marker for insulin resistance in PCOS." (PMID 39858445, 2025). "Insulin resistance was also highest in the highest free T quartile and lowest SHBG quartile." (PMID 38213908, 2024). "Low total testosterone and SHBG levels are strongly associated with an increased risk of metabolic syndrome independent of insulin resistance (IR)." (PMID 39768643, 2024). "Our study examines whether testosterone and SHBG serum levels may relate to insulin resistance in men on chronic hemodialysis." (PMID 39014506, 2024).
Insulin resistance (continued). "Six proteins function in regulating glucose homeostasis, insulin resistance, and β-cell function, including SHBG, FETUB, PRG4, GSN, CFD, and TF, among which SHBG and FETUB are markers of insulin sensitivity and the expression of TF in adipose tissue is positively associated with insulin sensitivity." (PMID 38182717, 2024). "In a prospective study including 3369 European men, lower baseline TT levels are related to an increased risk of incident MetS, independent of SHBG, BMI or insulin resistance." (PMID 38988998, 2024). "As the improvement of insulin resistance usually concurs with the decrease in pancreatic insulin production, insulin may also play a role in inhibiting the hepatic production of SHBG." (PMID 38238336, 2024). "Metformin can treat insulin resistance in patients with PCOS by increasing SHBG concentrations." (PMID 38779450, 2024). "According to existing research, SHBG acts as a protective factor in female infertility through various mechanisms; lower SHBG levels result in elevated free testosterone and insulin resistance, increasing the likelihood of obesity and PCOS, and consequently, the risk of infertility." (PMID 38848344, 2024). "Furthermore, the SHBG levels in our study negatively correlated with the measures of insulin resistance – HOMA-R and serum insulin – both in healthy men and in non-diabetic men on chronic hemodialysis." (PMID 39014506, 2024). "This suggests that a reduction in SHBG synthesis in the liver could lead to insulin resistance and decreased androgen bioavailability." (PMID 38848344, 2024). "Furthermore, studies confirm the presence of insulin resistance, low levels of total testosterone and decreased levels of sex hormone binding globulin (SHBG) in MS cases, particularly in older men." (PMID 39596286, 2024). "In the subgroup analyses, the significant association between SHBG level and Mets was detected in subjects over 60 years or older, with normal BMI, without insulin resistance, and with eGFR ≥90 mL/min per 1.73m2." (PMID 38988998, 2024). "Research demonstrated that SHBG levels are closely associated with central obesity, BMI, HDL, apolipoprotein B (apoB) and insulin levels in women, with the strongest correlation being with insulin resistance." (PMID 38892323, 2024). "SHBG production is lower in PCOS women with insulin resistance." (PMID 38592037, 2024). "The research suggests that SHBG plays a crucial role in insulin sensitivity, and its decrease may indicate the occurrence of insulin resistance." (PMID 38779450, 2024). "Decreased lipocalin levels and increased inflammatory factors such as tumor necrosis factor and interleukin 1β can inhibit SHBG production and SHBG may be an early marker of insulin resistance and disorders of glucose and lipid metabolism." (PMID 38988998, 2024). "Insulin resistance is accompanied by hyperinsulinism, which increases the levels of free androgen in the plasma by reducing the production of sex hormone-binding globulin, and high levels of androgen and insulin in the plasma can affect endometrial cell differentiation." (PMID 36964546, 2023). "In addition, enhanced insulin resistance secondary to obesity can contribute to the reduction in sex hormone binding globulin (SHBG) concentration in the blood." (PMID 37049573, 2023). "Insulin resistance suppresses SHBG synthesis, contributing to elevated androgen levels." (PMID 38288169, 2023). "Several risk factors increase the risk of GDM in women with PCOS, such as a high BMI, older age, increased free androgen index, insulin resistance, preconception impaired glucose tolerance, decreased SHBG, family history of type 2 diabetes mellitus, and even hypothyroidism." (PMID 38234933, 2023). "In addition, a low serum SHBG level is related to insulin resistance (IR) and, hence, is considered an indicator of abnormal metabolism." (PMID 37065734, 2023).
Insulin resistance (continued). "This suggests that SHBG may be involved in PI3K/protein kinase B (Akt) pathway-mediated systemic insulin resistance." (PMID 37452264, 2023). "Our study suggests that the cut-off point for HOMA-IR discriminating the insulin resistance based on the SHBG level, in young Caucasian women with polycystic ovary syndrome is 2.1, and is consistent with the cut-off value adopted by the European Group for the Study of Insulin Resistance (above 2.0)." (PMID 36968815, 2023). "Concordantly, we hypothesized that SHBG level may be a useful marker of the severity of hepatic insulin resistance." (PMID 36968815, 2023). "Contrary to the detectable cut-off point characterizing insulin resistance, the laboratory assays for SHBG have specified reference ranges and its lower limit may be used to establish a corresponding HOMA-IR cut-off point." (PMID 36968815, 2023). "PCOS is primarily characterized by infertility, hyperandrogenism, lack of ovulation, increased levels of LH, increased insulin resistance, decreased sex hormone-binding globulin (SHBG), and hirsutism, which can be seen and diagnosed by ultrasonography and laboratory tests." (PMID 37383339, 2023). "Insulin resistance has been observed to enhance the production of androgens in cells through the stimulation of luteinizing hormone, while concurrently impeding the synthesis of sex hormone binding globulin (SHBG) in liver cells." (PMID 37993900, 2023). "SHBG is regulated by insulin, and insulin resistance decreases its synthesis and secretion." (PMID 38317710, 2023). "In addition, RWG-induced insulin resistance and hyperinsulinemia lower the levels of sex hormone-binding globulin, resulting in the increased concentration and bioavailability of free sex hormones." (PMID 37522114, 2023). "The positive relationship between obesity, adiposity, and BMD has been emphasized, which is frequently observed in patients with PCOS; insulin resistance (IR) and increased insulin levels reduce sex hormone-binding globulin (SHBG) and increase the amount of free androgens." (PMID 38222239, 2023). "Nevertheless, the exact molecular impact of SHBG on adipose tissue metabolism, inflammation and insulin resistance remains elusive, and more advanced investigations are needed to clarify the possible use of the glycoprotein as a therapeutic agent for metabolic disorders management." (PMID 38146533, 2023). "Factors apt for further investigation include the extent to which PCOS phenotypes, BMI, obesity, insulin resistance, hyperandrogenemia, SHBG, hs-CRP, CTRP6, adiponectin, plasma leptin, homocysteine, AMH and thrombophilia contribute to further risk of miscarriage." (PMID 38027110, 2023). "Therefore, the aim of this study was to estimate the cut-off value for HOMA-IR discriminating the insulin resistance based on the SHBG level in women with PCOS." (PMID 36968815, 2023). "Our study suggests that the cut-off point for HOMA-IR discriminating the insulin resistance based on the SHBG level in young Caucasian women with PCOS is 2.1 and is consistent with the cut-off value adopted by the European Group for the Study of Insulin Resistance (above 2.0)." (PMID 36968815, 2023). "We hypothesize that this observation may also apply to premenopausal women, as recently published data show the similar predictive significance of SHBG levels for the development of insulin resistance in pre- and postmenopausal women." (PMID 36968815, 2023). "This could be due to a reduction in adipose tissue and/or insulin resistance, which increase SHBG levels, with a consequent reduction in free androgen levels." (PMID 36140277, 2022). "The hypocaloric low glycemic index (LGI) diet contributed to healthy weight loss, improved SHBG, and decreased homeostatic model assessment of insulin resistance (HOMA-IR) in people with and without PCOS." (PMID 35493382, 2022). "Also, a 6-year follow-up study that included 1,377 subjects showed that SHBG level is a marker of insulin resistance development." (PMID 35140785, 2022).
Insulin resistance (continued). "Therefore, this study aimed to assess the value of prediction of insulin resistance and impaired fasting glucose based on SHBG level in women with PCOS." (PMID 35140785, 2022). "Hyperinsulinemia is a compensatory mechanism for liver insulin resistance (IR); thus, SHBG may be considered as a surrogate marker of liver IR." (PMID 35140785, 2022). "Given that SHBG may be a potential biomarker for insulin resistance in PCOS, more research on the natural history evidence and impact on biochemical hyperandrogenism as a diagnostic feature in PCOS is needed." (PMID 35535684, 2022). "Due to FPLD-related insulin-resistance, SHBG is often low, which may lead to underestimation of total testosterone." (PMID 35440056, 2022). "Metabolic derangements were seen more in obese PCOS women in our study which was similar to a study done by Li and co-workers, who found a higher level of free androgen index, higher prevalence of insulin resistance, and lower sex hormone binding globulin (SHBG) levels in their PCOS cohort group." (PMID 35642189, 2022). "It is related to insulin resistance and compensatory hyperinsulinism, which in turn augments the action of luteinizing hormone (LH) on the theca cells, increasing androgen synthesis and reducing hepatic synthesis of sex-hormone-binding globulin (SHBG)." (PMID 36421197, 2022). "SHBG levels are known to be inversely related to obesity and insulin-resistance." (PMID 36303865, 2022). "Menstrual dysfunction in obese women may be related to insulin resistance/hyperinsulinemia, decreased sex hormone-binding globulin, and alterations in the hypothalamic–pituitary–ovarian axis." (PMID 36050702, 2022). "Hormonal changes with ageing and menopause such as a rapid fall in oestrogen levels, higher testosterone levels and lower sex hormone-binding globulin are associated with increase in body weight, redistribution of FM, decrease in FFM, insulin resistance and Type 2 DM in women compared to men." (PMID 35242108, 2022). "Given the hyperandrogenism and insulin resistance condition of PCOS, it has been proposed that mutations of the genes responsible for SHBG synthesis may also be responsible for PCOS." (PMID 36235799, 2022). "We observed 10% probability of insulin resistance occurrence at an SHBG concentration of 111.1 nmol/L, 20% at 85.3 nmol/L, 25% at 76.1 nmol/L, 33.3% at 63.2 nmol/L, and 50% at 41.1 nmol/L, while the probability of IR for an SHBG concentration of 26.1 nmol/L was 61.6% (95% CI: 57.4–65.8)." (PMID 35140785, 2022). "Obesity-related insulin resistance (IR) may induce excessive luteinizing hormone (LH)-stimulated ovarian androgen production and suppress hepatic sex hormone-binding globulin (SHBG) production, thus leading to HA." (PMID 36060969, 2022). "Based on that assumption, the following sections will present the available evidence on the potential implication of some biomediators, in particular hyperandrogenism, estrogen-progesterone imbalance, insulin-resistance, and low SHBG, in the processes leading to CV disease in PCOS." (PMID 34572562, 2021). "The elevated homeostatic model assessment of insulin resistance (HOMA-IR) observed in the PCOS group in our study may also contribute to the regulation of serum SHBG." (PMID 34805198, 2021). "In obese patients, hyperinsulinemia, which is induced by insulin resistance, may reduce the production of SHBG by the liver, resulting in estrogen demonstrating greater biological activity." (PMID 34940598, 2021). "In this 5–10 year follow-up of the PregMet-study, we assessed adrenal, gonadal and adipose tissue steroid hormones related to PCOS, in addition to hepatic sex-hormone-binding globulin (SHBG), which is inversely associated with obesity and insulin resistance; and calculated free testosterone." (PMID 34499672, 2021).
Insulin resistance (continued). "There is an established relationship between obesity and insulin resistance, obesity can also have a role in other abnormalities like excess production of androgens and estrogen from ovaries and a decrease in production of sex hormone binding globulin (SHBG) from liver." (PMID 34012539, 2021). "The excess of adipose tissue also causes increased expression of aromatase—an enzyme that converts androgens to estrogens—and insulin resistance results in a reduced production of sex hormone binding globulin (SHBG), which leads to an increase in the bioavailability of estrogens." (PMID 33562380, 2021). "Patients with obesity and insulin resistance show reduced circulating SHBG levels." (PMID 34335746, 2021). "Physical activity may lead to elevated SHBG concentrations by reducing low-grade inflammation, altering factors related to insulin resistance and possibly reducing liver fat; these physiological changes may be due to modifications in body composition." (PMID 34216337, 2021). "During follow-up, SHBG measurement may need to be repeated if obesity or insulin resistance develop or worsen." (PMID 34640379, 2021). "Moreover, hyperinsulinemia/insulin resistance is a major factor responsible for increased occurrence of sex-hormone-related cancers via downregulation of sex-hormone-binding globulin (SHBG) leading to elevated estrogen and testosterone bioavailability." (PMID 34208589, 2021). "Genetic studies also found that the causal relationship between SHBG, insulin resistance and diabetes is weak, indicating that the correlation was partially confounded rather than directly endowed by circulating SHBG." (PMID 34977197, 2021). "Although the clear mechanism between SHBG and insulin resistance is not fully understood, it is found that SHBG could affect glucose transporters and the PI3K/AKT pathway." (PMID 33101409, 2020). "Insulin resistance decreases SHBG levels resulting in lower total testosterone levels." (PMID 33312198, 2020). "SHBG is now considered as a surrogate marker of insulin resistance in PCOS diagnosis." (PMID 33033446, 2020). "Insulin resistance and compensatory hyperinsulinaemia could increase ovarian androgen production and reduce hepatic sex-hormone binding globulin (SHBG) production, resulting in androgen excess." (PMID 33101210, 2020). "In addition, it is now accepted that suboptimal levels of SHBG and testosterone significantly contribute to insulin resistance and therefore a pre-diabetic state." (PMID 32636807, 2020). "In addition to significant and sustained weight loss, several studies have also demonstrated improvement in total testosterone, SHBG levels, insulin resistance, and several other metabolic parameters." (PMID 32636807, 2020). "Accordingly, SHBG has emerged as a biomarker of insulin resistance." (PMID 33139661, 2020). "In women, insulin resistance might play a major role in the development of androgen excess by modulation of SHBG concentrations, as well as by direct effects on adrenal androgen secretion." (PMID 32535783, 2020). "The metabolic phenotype (non-reproductive group) with insulin resistance and low SHBG levels is at a high risk for infertility." (PMID 33139661, 2020). "In addition, our study suggested that normal weight women with PCOS showed higher TG, lower SHBG levels, and a trend towards increased insulin resistance." (PMID 31462934, 2019). "In summary, our study suggests potential causal association between decline in SHBG level and development of insulin resistance before menarche, but not after." (PMID 30925463, 2019). "Our study confirm these well-known pubertal-related patterns and further demonstrates temporal stability in SHBG and insulin resistance levels from childhood to early adulthood, a phenomenon that is likely explained partly by genetic factors, and/or early life programming." (PMID 30925463, 2019).